SUCNR1 (succinate receptor 1)
Description:
G protein-coupled receptor for succinate able to mediate signaling through Gq/GNAQ or Gi/GNAI second messengers depending on the cell type and the processes regulated (By similarity). Succinate-SUCNR1 signaling serves as a link between metabolic stress, inflammation and energy homeostasis. In macrophages, plays a range of immune-regulatory roles. During inflammation, succinate-SUCNR1 signaling may act as an anti-inflammatory mediator or boost inflammation depending on the inflammatory status of cells (By similarity). Hyperpolarizes M2 macrophages versus M1 phenotype through Gq signaling by regulating the transcription of genes involved in immune function. In activated M1 macrophages, plays a pro-inflammatory role in response to LPS (By similarity). Expressed in dendritic cells, where it is involved in the sensing of immunological danger and enhances immunity. Mediates succinate triggered intracelleular calcium mobilization, induces migratory responses and acts in synergy with Toll-like receptor ligands for the production of proinflammatory cytokines as well as an enhancement of antigen-specific activation of helper T cells. In the small intestine, mediates the activation of tuft cells by dietary succinate and triggers type 2 immunity (By similarity). In adipocytes, plays an important role in the control of energy metabolism. In response to succinate, controls leptin expression in an AMPK-JNK-CEBPA-dependent as well as circadian clock-regulated manner (By similarity). In muscle tissue, is expressed in non-muscle cells and coordinates muscle remodeling in response to the succinate produced during exercise training in a paracrine manner (By similarity). In retina, acts as a mediator of vessel growth during retinal development. In response to succinate, regulates the production of angiogenic factors, including VEGF, by retinal ganglion neurons (By similarity).
Synonyms: GPR91
Tractability: Small molecule: a structure with a bound ligand is known; a high-quality ligand is known; it belongs to a druggable protein family. Antibody: UniProt places it where antibodies can reach, with high confidence; its Gene Ontology location is reachable by antibodies, with high confidence; UniProt predicts a signal peptide or a membrane-spanning region. PROTAC: a small molecule that binds it is known.
Target class: Membrane receptor; Family A G protein-coupled receptor; Small molecule receptor (family A GPCR); Succinate receptor; Carboxylic acid receptor
Gene: Protein-coding gene on chromosome 3 (151,873,643 to 151,884,619, forward strand). Ensembl gene ENSG00000198829.
Subcellular location: Cell membrane
Pathways (Reactome):
Signal Transduction: Class A/1 (Rhodopsin-like receptors); G alpha (i) signalling events
Gene Ontology:
Molecular function: G protein-coupled receptor activity; protein binding; signaling receptor activity
Biological process: G protein-coupled receptor signaling pathway; energy homeostasis
Cellular component: extracellular exosome; plasma membrane; membrane
Genetic constraint (gnomAD): Loss-of-function variants: 5 observed, 1.61 expected, observed/expected ratio (o/e) 3.11. That is too few expected variants to judge how well the gene tolerates losing a copy. Missense variants: 366 observed, 415.3 expected, observed/expected ratio (o/e) 0.88, 90% interval 0.81 to 0.96. Synonymous variants: 159 observed, 150.35 expected, observed/expected ratio (o/e) 1.06, 90% interval 0.93 to 1.21.
Homologues: Orthologues: chimpanzee SUCNR1 (99% identical), macaque SUCNR1 (93% identical), dog SUCNR1 (82% identical), pig SUCNR1 (78% identical), rat Sucnr1 (71% identical), rabbit SUCNR1 (70% identical), mouse Sucnr1 (68% identical), guinea pig SUCNR1 (62% identical). Paralogues in human: P2RY1 (33% identical), OXGR1 (32% identical), P2RY2 (30% identical), P2RY4 (28% identical), P2RY6 (28% identical), HCAR2 (22% identical), HCAR3 (21% identical), GPR31 (21% identical), HCAR1 (21% identical), GPR42 (20% identical), FFAR3 (20% identical), FFAR2 (20% identical), and 3 more.
Diseases named in the same sentence as SUCNR1 in open-access papers:
SUCNR1 is named in the same sentence as 112 diseases in open-access papers, as found by Europe PMC text mining. Sharing a sentence is not in itself a finding about the gene and the disease. The quoted sentences say what the papers report.
Obesity (32 papers, 2017 to 2025). Accumulation of substantial excess body fat. "While the succinate/SUCNR1 signaling axis is implicated in obesity pathogenesis, its association with serum metabolite profiles remains unexplored." (PMID 41178975, 2025). "Elevated succinate levels are associated with obesity pathogenesis primarily through the activation of succinate receptor 1 (SUCNR1 or GPR91)." (PMID 40183584, 2025). "While obesity is associated with increased succinate levels, it often features impaired SUCNR1 signaling, leading to what is described as a “succinate-resistant state”." (PMID 38933270, 2024). "Correspondingly, SUCNR1 signaling has been primarily linked to pathophysiology, including metabolic disorders such as obesity, diabetes, and non-alcoholic fatty liver disease." (PMID 38713514, 2024). "For example, SUCNR1, the succinate receptor, has recently been found to upregulate the expression of the markers associated with M2 macrophage in obesity." (PMID 34122419, 2021). "Therefore, succinate-SUCNR1 signaling can be considered as a metabolic guardian in both the steady state as well as obesity-associated chronic inflammation in VAT." (PMID 34421909, 2021). "SUCNR1-mediated macrophage chemotaxis aggravated obesity-associated inflammation and metabolic disorders, and this study indicates that SUCNR1 may be an essential therapeutic target in obesity-induced diseases." (PMID 34421909, 2021). "Interestingly, obesity is associated with higher circulating levels of succinate but impaired SUCNR1-signaling, which we have termed a succinate-resistant state." (PMID 31654259, 2019). "Indeed, a bulk of evidences point to SUCNR1 as a masterpiece in the etiology of some disturbances associated with obesity and T2D." (PMID 31654259, 2019). "Succinate is released in response to metabolic stress and has been shown to play a pro‐inflammatory role in obesity via the succinate receptor 1 (SUCNR1)." (PMID 40350961, 2025). "In adipocytes, SUCNR1 is, besides its anti‐lipolytic role, responsible for intact glucose homeostasis and prevents metabolic consequences of diet‐induced obesity." (PMID 39838520, 2025). "Many studies have focused on SUCNR1 function in both adipocytes and macrophages in the context of obesity." (PMID 39838520, 2025). "Succinic acid receptor (SUCNR1) signalling from macrophages has been suggested as a possible mechanism for resolving obesity related inflammation." (PMID 39770979, 2024). "Succinate and its receptor SUCNR1 exacerbate this obesity-induced inflammation, promoting the infiltration of macrophages into adipose tissue, which is a key contributor to the glucose intolerance observed in type 2 diabetes." (PMID 38933270, 2024). "The observed upregulation of SUCNR1 in human islets during obesity and diabetes, coupled with evidence from our β cell SUCNR1 knockout model, points to a compensatory mechanism aimed at counteracting metabolic challenges." (PMID 38713514, 2024). "Accordingly, SUCNR1 expression is significantly greater in islets from donors with obesity and T2D than in lean control donors, which fits with our previous findings of higher circulating succinate levels in the former." (PMID 38713514, 2024). "Altogether, these data demonstrate that SUCNR1 plays an essential role in insulin secretion in vivo, particularly in an obesity context." (PMID 38713514, 2024). "For example, SUCNR1 has recently been reported to increase the expression of the anti-inflammatory markers related to M2 macrophages in WD induced obesity." (PMID 35281054, 2022). "SUCNR1 can regulate the metabolic response to obesity, with the succinate–SUCNR1 axis serving as a link between metabolic stress and inflammation." (PMID 35807856, 2022). "The anti-inflammatory effect of the succinate–SUCNR1 axis in attribution to obesity and cancer convincingly suggests a role of succinate and SUCNR1 in driving anti-inflammatory responses." (PMID 32942769, 2020).
Obesity (continued). "This enables the study of the role of SUCNR1 in obesity-induced inflammation and metabolic disturbances independent of changes in body weight or adipose tissue weight." (PMID 28382382, 2017). "Our results reveal that activation of SUCNR1 in macrophages is important for both infiltration and inflammation of adipose tissue in obesity, and suggest that SUCNR1 is a promising therapeutic target in obesity-induced type 2 diabetes." (PMID 28382382, 2017). "As such, our data put forward SUCNR1 as a promising therapeutic target to combat obesity-induced diabetes." (PMID 28382382, 2017). "For instance, E. cloacae and C. aerofaciens may elevate succinate levels, activating SUCNR1 and fostering inflammation, which disrupts metabolic homeostasis and exacerbates obesity." (PMID 40183584, 2025). "Nevertheless, findings from non-pregnant studies indicate that succinate may act as a signalling metabolite influencing insulin secretion and obesity-induced inflammation, and expression of the succinate receptor SUCNR1 has been demonstrated in human placenta." (PMID 41202005, 2025). "To evaluate whether Sucnr1 is regulated in the pancreas in different metabolic states, we first assessed its expression in total pancreas tissue from rodent models of obesity and T2D." (PMID 38713514, 2024). "Despite the absence of incretin response both in Sucnr1-βKO mice and control mice in diet-induced obesity, β cells in Sucnr1-βKO mice fall short in counteracting hyperglycemia, which emphasizes the critical involvement of the succinate/SUCNR1 axis in this scenario." (PMID 38713514, 2024). "As a result, we propose that SUCNR1 exerts its primary influence on the functionality of adult β cells, rather than on their development or the typical compensatory alterations in β cell mass observed during obesity." (PMID 38713514, 2024). "To question whether specific β cell disruption of Sucnr1 affected glucose response in an obesity context, we performed a glucose tolerance test (GTT) in mice fed an HFD." (PMID 38713514, 2024). "SUCNR1 expression in islets is regulated in human obesity and T2D." (PMID 38713514, 2024). "Hence, a myeloid-specific knockout of Sucnr1 in mice led to local tissue inflammation and development of obesity." (PMID 37235648, 2023). "Previous studies have reported a role for SUCNR1 in acute colitis, arthritis, isoproterenol-induced myocardial ischemia, obesity and diabetes, but as far as we know, the present study was the first to show a role for this receptor in the in vivo regulation of inflammasome priming." (PMID 35327334, 2022). "However, succinate receptor SUCNR1 is an early detector to many physiological and pathological processes, including obesity, inflammation and cancer." (PMID 35757749, 2022). "DHDH is involved in the detoxication of trans-dihydrodiol and carcinogenic metabolites of polycyclic aromatic hydrocarbons; SUCNR1 is related to conditions such as hypertension, diabetes, and obesity, whereas ATP8B3 is involved in aminophospholipid transport in the liver." (PMID 36542226, 2022). "To test whether the beneficial metabolic effects of O. laneus are dependent on succinate as an extracellular signaling molecule, we repeated the probiotic intervention in wild-type and Sucnr1 knock-out mice after 8 weeks of HFD to induce obesity." (PMID 36002880, 2022). "Interestingly, the emerging evidence in obesity and tumors show that SUCNR1 acts as the vital anti-inflammation node in macrophage." (PMID 34122419, 2021). "In obesity, succinate, via SUCNR1, may enhance or impair macrophage inflammation, leaving it unclear whether exogenous succinate might be beneficial in HFD‐induced obesity." (PMID 33185326, 2020). "We aimed to evaluate whether SUCNR1 and its ligand, succinate, have an important role in the development and progression of obesity-induced inflammation and insulin resistance in type 2 diabetes." (PMID 28382382, 2017).
Obesity (continued). "The dichotomous effects of SUCNR1 on the development of obesity in their experiments could possibly result from the specific Cre model used to generate their Sucnr1−/− mouse or the different diets/intervention periods." (PMID 28382382, 2017). "SUCNR1 knockout mice exhibited reduced adipocyte size, increased energy expenditure, and improved glucose regulation, yet long-term high-fat diets led to increased adiposity, hyperglycemia, and liver damage, emphasizing SUCNR1’s nuanced role in energy sensing and obesity." (PMID 40183584, 2025). "Indeed, we recently demonstrated that SUCNR1 signaling in adipose tissue-resident macrophages is key for the resolution of acute inflammation––a physiological process that is inoperative in human obesity." (PMID 36002880, 2022). "Moreover, the succinate-SUCNR1 signaling acted as a major driver of microbiota-triggered type 2 immunity in the intestine and was described as an anti-inflammatory mediator to regulate the metabolic response to obesity in macrophages." (PMID 35309330, 2022). "Similarly, a recent study from our laboratory has uncovered a hitherto unrecognized mechanism whereby SUCNR1 signaling in macrophages is key for the active resolution of acute inflammation in the context of obesity – a physiological circuit broken in human obesity." (PMID 31654259, 2019). "SUCNR1 may nevertheless have an important signalling function, especially during obesity-induced macrophage infiltration in adipose tissue; this is supported by our in vitro data showing enhanced SUCNR1 expression in murine macrophages exposed to adipose tissue explants." (PMID 28382382, 2017). "Similarly, while the inhibition of SUCNR1 has been proposed as a strategy to alleviate various inflammatory conditions, its blockade might be detrimental in treating inflammation and glucose intolerance in obesity." (PMID 38182909, 2024). "Succinate receptor 1 (SUCNR1) activation mediates macrophage infiltration and inflammation in obesity, as evidenced by how Sucnr1−/− mice displayed decreased macrophage numbers and increased glucose tolerance." (PMID 32646451, 2020). "We conclude that the absence of SUCNR1 protects against the development of obesity-induced adipose tissue inflammation and glucose intolerance." (PMID 28382382, 2017). "Noticeably, during the development of obesity in WT mice, Sucnr1 expression levels in adipose tissue did not change (data not shown)." (PMID 28382382, 2017). "Therefore, we suggest that succinic acid may activate the P38/MAPK and AKT signaling pathways through the receptor SUCNR1, promoting fat browning and resisting HFD-induced obesity." (PMID 39599615, 2024). "Additionally, succinate receptor 1 (SUCNR1) may play a pivotal role in the pathogenesis of T2DM and obesity." (PMID 37047729, 2023).
diabetes (22 papers, 2015 to 2025). "We aim to provide an overview of the role of the succinate–succinate receptor 1 (SUCNR1) axis in diabetes, discussing the potential use of succinate as a biomarker and the novel prospect of targeting SUCNR1 to manage complications associated with diabetes." (PMID 38182909, 2024). "This section aims to provide a comprehensive review of the current knowledge on the interplay between diabetes and the succinate–SUCNR1 axis, shedding light on the underlying mechanisms and potential therapeutic implications." (PMID 38182909, 2024). "Research highlights the association between abnormal succinate levels, hyperactivation of SUCNR1 and various disorders, including diabetes and its related complications." (PMID 38182909, 2024). "SUCNR1 antagonists offer potential benefits in counteracting the harmful effects of succinate signalling observed in diabetes, promising a reduction in inflammation and metabolic balance restoration." (PMID 38182909, 2024). "SUCNR1’s expression extends to tubular cells, which are the predominant producers of (pro)renin in individuals with diabetes." (PMID 38182909, 2024). "Recent work has also highlighted the interaction between iron, SUCNR1 and the renin–angiotensin system in diabetes-related neurodegeneration and vascular abnormalities, stressing the role of iron homeostasis in preventing retinal oxidative stress." (PMID 38182909, 2024). "SUCNR1, also known as GPR91, is a member of the G protein-coupled receptor family, exhibiting a high potential as a drug target in human diseases, such as hypertension and diabetes." (PMID 36035205, 2022). "We further propose strategies to manipulate the succinate–SUCNR1 axis for better diabetes management; this includes pharmacological modulation of SUCNR1 and innovative approaches to manage succinate concentrations, such as succinate administration and indirect strategies, like microbiota modulation." (PMID 38182909, 2024). "Inhibiting SUCNR1 could prevent diabetes-related retinal neovascularisation and kidney disease, although these potential benefits have yet to be scientifically substantiated." (PMID 38182909, 2024). "The role of succinate and SUCNR1 in diabetes will be further explored in the subsequent sections." (PMID 38182909, 2024). "Maintaining a balanced succinate–SUCNR1 axis may be crucial for optimal physiological functioning, with dysregulation potentially contributing to diseases like diabetes." (PMID 38182909, 2024). "Moreover, striking a balance between blocking the harmful effects of SUCNR1 while maintaining its beneficial ones offers a promising path for novel diabetes treatments." (PMID 38182909, 2024). "We must fully uncover the mechanisms driving succinate–SUCNR1 signalling and their impact on disease progression; this knowledge could help to develop interventions to curb succinate’s detrimental effects in diabetes, improving patient outcomes." (PMID 38182909, 2024). "Moreover, the role of SUCNR1 has been suggested in the development of fibrosis in diabetes mellitus and other diabetes-related complications such as diabetic retinopathy and metabolic syndrome." (PMID 38674089, 2024). "The succinate–SUCNR1 axis, with SUCNR1 acting as a GPCR, presents a promising target for innovative diabetes therapies." (PMID 38182909, 2024). "Sustained elevations in succinate, and subsequent activation of the G protein‐coupled receptor 91 (GPR91) or succinate receptor (SUCNR1), may also be indicative of mitochondrial stress due to hypoxia, diabetes, or cancer (Peti‐Peterdi, 2010)." (PMID 33185326, 2020).